H19 (H19 imprinted maternally expressed transcript)
Diseases named in the same sentence as H19 in open-access papers (continued):
Sharing a sentence is not in itself a finding about the gene and the disease.
lung carcinoma (continued). "The lncRNA H19 is induced by c-Myc favoring the development of breast and lung cancers." (PMID 26461935, 2015). "Furthermore, we recently provided evidence that H19 lncRNA significantly promotes the metastasis of lung cancer cells in vivo." (PMID 25884481, 2015). "Knocking down H19 lncRNA in hypoxia inhibits lung cancer cell proliferation." (PMID 25884481, 2015). "Further support for the involvement of H19 in lung cancer can be found in other reports." (PMID 25884481, 2015). "Lung cancer patients with high expression levels of mdig and H19 manifest poorer survival." (PMID 25884481, 2015). "Strong support for the linkage between lung cancer development and H19 lncRNA expression was provided by a study that revealed that smokers have dramatically elevated H19 lncRNA levels without alternation of the expression levels of other imprinted genes in the cluster." (PMID 25884481, 2015). "Because we noted that mdig enhanced H19 expression by demethylating H3K9me3 in the promoter and ICR region of the H19 gene, we next aimed to determine whether higher levels of H19 also predict a poorer prognosis for the lung cancer patients." (PMID 23965803, 2013). "Indeed, a highly significant inverse correlation of higher H19 expression as determined by probe set 217723_x_at with the poorer overall survival of total lung cancer patients was observed." (PMID 23965803, 2013). "Recently, upregulation of PKM2 was reported in erlotinib-resistant lung cancer cells; mechanistically, this might be due to a decrease in long non-coding (lnc) RNA H19-mediated, ubiquitin-induced PKM2 degradation, such that PKM2 confers resistance to erlotinib through phosphorylation of AKT." (PMID 36611972, 2023). "In another study on the mechanism of lung cancer, it was found that lncRNA H19 may inhibit the transcription level of FTH1 by competitively binding miRNA-19b-3p, so as to protect lung cancer cells from iron death injury, thus weakening the effect of anticancer drugs." (PMID 35844870, 2022). "Similarly, H19 was shown to interact with miR-140-5p in lung cancer." (PMID 34250088, 2021). "Moreover, H19 was involved in methylation-mediated lung cancer progression." (PMID 34421359, 2021). "Recently it was revealed that mineral dust-induced gene (mdig) enhances H19 expression by influencing the heterochromatin structure through reduction in the level of H3K9me3 in the promoter as well as ICR region of the H19 gene in adenocarcinoma lung cancer cells." (PMID 25884481, 2015). "For examples, Research has identified particular lncRNAs, such as H19 and HOTAIR, that are overexpressed in lung cancer and contribute to resistance against targeted therapies like TKIs." (PMID 39912974, 2025). "An exemplary lncRNA in this context is H19, which modulates the transforming growth factor-beta (TGF-β) signaling pathway in lung cancer." (PMID 39201688, 2024). "Taken together, these findings highlight the potential efficacy of β-elemene as a novel approach to overcome lncRNA H19-mediated autophagy-induced degradation of EGFR and combat resistance to gefitinib in lung cancer." (PMID 38794196, 2024). "Particularly, H19, NEAT1, SNHG1, and TUG1 were significantly more expressed in lung cancer patients from both AA and WA lung cancer patients compared to those without cancer." (PMID 38791954, 2024). "For instance, lncRNA H19, initially identified as a regulator of embryonic development and imprinting, exhibits dysregulated expression in COPD and lung cancer tissues." (PMID 39201688, 2024). "Up-regulation of lncRNA H19 induces ferroptosis and enhances the sensitivity of EGFR-TKI resistant lung cancer to erlotinib." (PMID 38515565, 2024).
lung carcinoma (continued). "It has been demonstrated by several studies that some lncRNAs, including SBF2-AS1, H19, and OR3A4, have a wide range of applications in the diagnosis and treatment of lung cancer." (PMID 36711024, 2023). "LncRNAs have become the key regulatory factors in development and progression of lung cancer, functioning as oncogenes (e.g., MALAT1, HOTAIR, H19 and ANRIL) or tumor suppressors (e.g., MEG3, GAS5, and TUG1)." (PMID 34976181, 2022). "H19 acts as the “ceRNA” of miR-19b-3p and promotes the expression of FTH1, which plays a promoting role in lung cancer." (PMID 36188624, 2022). "Both Curcumenol and Ginsenoside Rb3 inhibit H19 expression through the H19/miR-19b-3p/FTH1 axis and the H19/miR-29b-3p/HGMB1/TLR4 axis to promote ferroptosis in lung cancer cells and reduce inflammation." (PMID 36188624, 2022). "Several lncRNAs such as H19, MALAT1, and DANCR act as oncogenes in lung cancer by interacting with miRNAs." (PMID 33412752, 2020). "It has been shown that miR-3611 is significantly down-regulated in a H19 knockdown lung cancer cell line (SPC-A1), which indicated overexpression of this miR in ‘normal’ H19 intact lung cancer cell lines." (PMID 32512929, 2020). "Several lncRNAs that function as oncogenes in lung cancer have been identified, for example, lncRNA H19 is highly expressed in the A549, H1299, H23, and SPC-A1 lung cancer cell lines, and inhibits miR-200a, miR-196b, and miR-29b-3p." (PMID 33412752, 2020). "To date, only a few lncRNAs (including MALAT1, HOTAIR, H19, MEG3, GAS5, ANRIL, and SOX2OT etc.)have been reported to be dysregulated and functionally characterized in lung cancer and most of the studies were based on microarray expression data." (PMID 26862852, 2016). "We have identified some lncRNAs including lncRNA UCA1, H19, BC200 and BC087858 were up-regulated in gefitinib-resistant human lung cancer cells by lncRNA microarray analysis." (PMID 27409677, 2016). "The combined expression levels of H19 lncRNA and IGF2 driven by P4 promoter in lung cancer patients is higher than each one alone, so the use of this vector should substantially increase the therapeutic index." (PMID 25884481, 2015). "While lncRNAs in lung cancer is still an emerging field, several have been shown to be involved in tumorigenesis, including HOTAIR, H19, ANRIL, and MALAT1." (PMID 22852089, 2012). "For example, in a lung cancer (LC) relapse model, butyrate derived from Roseburia inhibited HDAC2, increased H3K27 acetylation at the H19 promoter, and induced M2 macrophage polarization, thereby increasing the expression of H19 in tumor cells and promoting lung cancer metastasis." (PMID 41355959, 2026). "In lung cancer cells, butyrate produced by Roseburia suppresses HDAC2 expression and activity, thereby reducing its deacetylation of histone H3K27 in the vicinity of the H19 promoter and leading to transcriptional activation of H19." (PMID 41516132, 2025). "In lung cancer, low-dose butyrate enhances tumour growth and metastasis through extracellular matrix remodelling, upregulation of MMP15, and HDAC2-dependent activation of the oncogenic lncRNA H19, which also promotes M2 macrophage polarization." (PMID 40925904, 2025). "This lncRNA H19/miR-19b-3p/FTH1 axis is crucial for mediating curcumenol-induced ferroptotic cell death, highlighting the role of ncRNAs in modulating the effects of natural compounds on ferroptosis in lung cancer." (PMID 39104501, 2024). "Therefore, H19 knockout influences proliferation, invasion, and metastasis by upregulating mir-484 and down-regulating ROCK2 to inhibit the EMT in lung cancer cells." (PMID 36188624, 2022).
lung carcinoma (continued). "LncRNA H19 is also highly expressed in lung cancer, and by inhibiting the function of miR-200a, upregulates the expression of ZEB1 and ZEB2, promoting the epithelial-mesenchymal transition and enhancing lung cancer cell proliferation and metastasis." (PMID 36406130, 2022). "The level of LINC00641 and H19 in lung cancer cell lines was found to be evidently lower than that in normal lung cell lines." (PMID 32869486, 2020). "In lung cancer, butyrate-producing microbial communities were found to upregulate genes related to H19, a long non-coding RNA (lncRNA), by inhibiting histone deacetylase 2 (HDAC2), thereby promoting histone H3 lysine 27 acetylation (H3K27 acetylation) and enhancing H19 promoter activity." (PMID 39921821, 2025). "Therefore, we speculated that the overexpression of Linc00485 elevated the expression of c‐Myc by sponging miR‐298, thereby activating multiple downstream genes including H19 and ANRIL, and thus driving lung cancer development." (PMID 33237626, 2021). "Mechanistically, H19 acts as a sponger of miR-19 to enhance STAT3 expression in lung cancer and it may also target miR-107, miR-21, miR-196b and miR-484 in different types of lung cancers." (PMID 32272875, 2020). "The high expression of H19 and miR-675 in lung tumors suggest that they could be used to detect lung cancer in fluid body like sputum (this has not yet been attempted)." (PMID 25884481, 2015). "The up-regulation of H19 was monoallelic and it was suggested that overexpression and eventual LOI of H19 may represent early markers in the progression of airway epithelium toward lung cancer." (PMID 25884481, 2015).
hepatocellular carcinoma (130 papers, 2007 to 2025). A malignant tumor that arises from hepatocytes. "H19 was the first lncRNA found to be implicated in ABCB1 regulation in human hepatocellular carcinoma (HCC)." (PMID 37781691, 2023). "For instance, miR503HG and its encoded miR-503 cooperatively inhibit tumor metastasis in hepatocellular carcinoma, and lncRNA H19 and miR-675 both promote tumor cell proliferation in CRC." (PMID 35279145, 2022). "Abnormal m5C modification of lncRNA H19 mediated by NSUN2 was associated with poor differentiation of hepatocellular carcinoma." (PMID 34917609, 2021). "In the clinical situation, several neoplasms including hepatocellular carcinoma, urothelial cell carcinoma and non-small cell lung cancer were found to be associated with the existence of LncRNA H19 SNP." (PMID 33799753, 2021). "The lncRNA H19, an evolutionarily conserved RNA (murine chromosome 7/human 11p15.5), has significant pathogenic associations with hepatic disorders, including metabolic-associated fatty liver disease, cholestatic injury, and hepatocellular carcinoma (HCC)." (PMID 41287791, 2025). "H19 lncRNA, once recognized for its tumor-suppressive role, is now associated with the activation of lung, breast, and head-and-neck cancers, as well as promoting cell growth and proliferation in bladder and hepatocellular carcinoma (HCC)." (PMID 40703556, 2025). "H19 can be re-activated in adulthood during tissue-regeneration; however, increased levels of H19 have been associated with tumor development in many cancers, including hepatocellular carcinoma." (PMID 32101552, 2020). "The proliferation-suppressive actions of H19, as shown in the two human hepatoma cell lines Huh7 and Plc/Prf/5, could also be verified in vivo: H19 deficient long-term DEN-treated animals exhibited elevated Ki67 staining." (PMID 31225433, 2017). "Therefore, aim of this study was to determine the function of H19 in hepatocellular carcinoma (HCC), an inflammation-associated type of tumor." (PMID 31225433, 2017). "Besides that, H19 related chemoresistance in hepatocellular carcinoma cells was associated with induction of MDR1." (PMID 27845892, 2016). "H19 is upregulated in hepatitis B virus (HBV)-associated hepatocellular carcinoma (HCC)." (PMID 25119862, 2014). "The progression of hepatocellular carcinoma can be affected by the knockdown of the long noncoding RNA H19 (H19) in hepatocellular carcinoma cells, and the expression of H19 is associated with CDK6." (PMID 40486867, 2025). "Abundant expression of H19 is found in human cancers, including breast, ovary, colon and hepatocellular cancers and GC." (PMID 40868070, 2025). "Several reports have been made about lncRNA H19, hsa‐miR‐196b‐5p, and hsa‐miR‐96‐5p in hepatocellular carcinoma or other cancers or tumorigenesis." (PMID 40304434, 2025). "For example, H19 overexpression can improve renal function and alleviate acute kidney injury, as well as induce anoxia–reoxygenation injury through autophagy in hepatoma cells, and the inhibition of H19 protects against cerebral IRI in rats." (PMID 40076761, 2025). "Exosomal H19 has been shown to exacerbate hepatocellular carcinoma progression in response to propofol treatment." (PMID 40781643, 2025). "Aflatoxin B1 promotes the proliferation and invasion of hepatoma cells by increasing the expression levels of H19 and transcription factor E2F1." (PMID 38334963, 2024). "m5C writer NSUN2 acts as an oncogene to promote gastric cancer and hepatocellular carcinoma (HCC) development by regulating protein-encoding gene CDKN1C and lncRNA H19, respectively." (PMID 36806253, 2023). "In the progression and malignancy of hepatocellular carcinoma, NSUN2-mediated m5C modification of H19 lncRNA plays an important role in the process of mutation of the lncRNA." (PMID 37542290, 2023). "For example, several human studies have found that H19 is overexpressed in hepatocellular carcinoma." (PMID 35437883, 2022).
hepatocellular carcinoma (continued). "In contrast, in chemo-resistant cells, over-expression of H19 can reverse the drug resistance to doxorubicin, so that suppressing hepatocarcinogenesis and hepatoma cell growth." (PMID 36246634, 2022). "It has been reported that H19 mediated the development of cancer cells such as hepatocellular carcinoma by means of exosomes." (PMID 36188624, 2022). "During the progression of hepatocellular carcinoma, the expression level of H19 transcripts is found imbalanced high." (PMID 36246634, 2022). "The interaction between the lncRNA H19 and miR-193a-3p regulates the radiosensitivity of hepatocellular carcinoma cells." (PMID 34863180, 2021). "In hepatocellular carcinoma, it has been reported that H19 positively regulates CDC42 via sponging miR-15b." (PMID 34168124, 2021). "It has been reported that lncRNA H19 promotes hepatocellular carcinoma metastasis and invasion by triggering and activating the miR-193b/MAPK1 axis." (PMID 33403385, 2021). "It was demonstrated that inhibiting the expression of H19 in hepatocellular carcinoma cell lines reduced the ability of carcinoma cells to migrate and invade." (PMID 32337223, 2020). "Diverse LncRNAs function as ceRNAs to adjust the EMT progression, such as LncRNA of HULC in hepatocellular carcinoma and LncRNA of H19 in colorectal cancer." (PMID 33311443, 2020). "In conclusion, our results revealed that the NSUN2-mediated m5C modification of H19 lncRNA exert an important function in the progression and malignancy of hepatocellular carcinoma." (PMID 32978516, 2020). "In other models such as hepatocellular carcinoma, H19 has been demonstrated to induce both stemness and EMT to accelerate invasion of hepatocellular carcinoma cells in vitro." (PMID 33291403, 2020). "Besides, both the m5C methylation level and the expression level of H19 lncRNA in hepatocellular carcinoma tissues were significantly higher than those in adjacent non-cancer tissues, which were closely associated with poor differentiation of hepatocellular carcinoma (HCC)." (PMID 32978516, 2020). "Numerous data indicate that H19 promotes the EMT in various tissues, including the breast, but Zhang and collaborators demonstrated that H19 is implied in the metastasis suppression of hepatocellular carcinoma." (PMID 32610610, 2020). "The lncRNA H19 imprinted maternally expressed transcript (H19) is significantly upregulated in hepatocellular carcinoma, and confers growth, migration, and invasion advantages on cancer cells." (PMID 31871924, 2019). "In a doxorubicin-resistant hepatocellular carcinoma cell line, R-HepG2, it was found that knockdown of H19 resulted in an increase of promoter methylation at the MDR1 promoter." (PMID 28933364, 2017). "We therefore determined the action of H19 in three different human hepatoma cell lines (HepG2, Plc/Prf5, and Huh7)." (PMID 31225433, 2017). "H19 is expressed in highly proliferating tissues including fetal and postnatal livers, and H19 expression can reemerge in adult liver during hepatocellular carcinoma, or during regeneration after injury." (PMID 29099871, 2017). "H19 is expressed in liver during periods of increased cell proliferation, including liver regeneration after injury and hepatocellular carcinoma." (PMID 29099871, 2017). "Moreover, results show that the level of H19 RNA is elevated in the multi-drug resistant variant of hepatocellular carcinoma (HCC) cell lines." (PMID 26623562, 2016). "H19 was underexpressed in intratumoral hepatocellular carcinoma tissues (T) compared to peritumoral tissues (L), and a low T/L ratio of H19 was associated with shorter disease-free survival and can be used to predict poor prognosis." (PMID 26252651, 2015). "In this study, we demonstrate, for the first time to our knowledge, that H19 is highly expressed in a subpopulation of hepatoma cells that expose the surface antigen CD90 and are characterized, by others, as CSC-like cells." (PMID 26272696, 2015).